NEBL (nebulette)
Description:
Binds to actin and plays an important role in the assembly of the Z-disk. May functionally link sarcomeric actin to the desmin intermediate filaments in the heart muscle sarcomeres. [Isoform 2]: May play a role in the assembly of focal adhesions.
Synonyms: C10orf113; LNEBL; LASP2; bA165O3.1
Tractability: PROTAC: its protein half-life has been measured.
Gene: Protein-coding gene on chromosome 10 (20,779,973 to 21,293,011, reverse strand). Ensembl gene ENSG00000078114.
Subcellular location: Cytoplasm (Isoform 2)
Gene Ontology:
Molecular function: actin filament binding; cytoskeletal protein binding; filamin binding; protein binding; tropomyosin binding; structural constituent of muscle
Biological process: cardiac muscle thin filament assembly
Cellular component: cytoplasm; extracellular exosome; stress fiber; Z disc; I band
Genetic constraint (gnomAD): Loss-of-function variants: 72 observed, 84.54 expected, observed/expected ratio (o/e) 0.85, 90% interval 0.7 to 1.04. The upper end of that interval is the gene's LOEUF score, 1.04, which puts it in group 4 of 6, group 1 being the genes least tolerant of losing a copy. Missense variants: 953 observed, 945.09 expected, observed/expected ratio (o/e) 1.01, 90% interval 0.95 to 1.06. Synonymous variants: 326 observed, 317.85 expected, observed/expected ratio (o/e) 1.03, 90% interval 0.94 to 1.12.
Gene-disease validity (ClinGen):
ClinGen rates the evidence that NEBL causes each of these diseases.
dilated cardiomyopathy (autosomal dominant): Limited. Cardiomyopathy which is characterized by dilation and contractile dysfunction of the left and right ventricles.
Homologues: Orthologues: chimpanzee NEBL (99% identical), macaque NEBL (95% identical), dog NEBL (91% identical), mouse Nebl (88% identical), guinea pig NEBL (86% identical), pig NEBL (86% identical), rabbit NEBL (85% identical), rat Nebl (83% identical), tropical clawed frog nebl (65% identical), Caenorhabditis elegans ltd-1 (4% identical), Drosophila melanogaster Hil (4% identical). Paralogues in human: NEB (29% identical), NRAP (21% identical), LASP1 (12% identical), KY (6% identical).
Diseases named in the same sentence as NEBL in open-access papers:
NEBL is named in the same sentence as 52 diseases in open-access papers, as found by Europe PMC text mining. Sharing a sentence is not in itself a finding about the gene and the disease. The quoted sentences say what the papers report.
cardiomyopathies (11 papers, 2012 to 2025). "Studies in humans and experimental models have previously shown an association of NEBL gene mutations with the development of cardiomyopathy and endocardial fibroelastosis." (PMID 41472124, 2025). "Mutation of NEBL (actin-binding sarcomeric nebulette) has been shown to be associated with various cardiomyopathies including dilated cardiomyopathy." (PMID 39803589, 2024). "CSRP3 and NEBL bind actin and are important in maintaining muscle structure, with mutations causing cardiomyopathy in mammals." (PMID 31170930, 2019). "While the relatedness between this gene and cardiomyopathy is reported from many groups, NEBL is also associated with depression disorder." (PMID 22901090, 2012). "Some scientists hypothesize that variants in the NEBL gene are associated with various cardiomyopathies." (PMID 39765701, 2024). "NEBL isn’t considered to be a hallmark HCMP gene, however variants in this gene were previously associated with several types of cardiomyopathies, including HCMP, dilated cardiomyopathy and left ventricular non-compaction cardiomyopathy." (PMID 40442228, 2025). "The NEBL variant has been found in isolation in one Japanese patient with DCM and in conjunction with another cardiomyopathy-associated variant in a Japanese HCM patient." (PMID 32344918, 2020). "For the remaining MYH7 HCM samples, variants in the following other cardiomyopathy genes were also found: DSP, MHY6, NEBL, PSEN1, RBM20, and TTN." (PMID 32344918, 2020). "Similarly, RNA-binding motif protein 24 (RBM24) regulates a subset of genes associated with cardiomyopathies such as sarcomere z-disc genes TTN, nebulette (NEBL), and enah actin regulator (ENAH)." (PMID 38132114, 2023). "Pathogenic variants in NEBL and MYBPC3 have been associated with cardiomyopathies." (PMID 34816733, 2021).
colorectal cancer (6 papers, 2017 to 2025). A primary or metastatic malignant neoplasm that affects the colon or rectum. "In colorectal cancer, survival analysis showed that patients with high expression of NEBL had a long overall survival." (PMID 41425852, 2025).
dilated cardiomyopathy (4 papers, 2020 to 2025). "The pathogenic mutations of NEBL will induce dilated cardiomyopathy, hypertrophic cardiomyopathy, left ventricular non-compaction cardiomyopathy, and endocardial fibroelastosis." (PMID 36303204, 2022).
22q11.2 deletion syndrome (2 papers, 2023 to 2024). 22q11.2 deletion syndrome (DS) is a chromosomal anomaly which causes a congenital malformation disorder whose common features include cardiac defects, palatal anomalies, facial dysmorphism, developmental delay and immune deficiency. "Although 22q11.2 deletion syndrome and chromosomal abnormalities were ruled out in this case, a genetic etiology could not be ruled out as the patient was not evaluated for other genetic abnormalities such as NEBL, TBCE, FAM111A, CASR, and GNA11 mutations." (PMID 36865979, 2023). "However, we also found variants in genes associated with primary hyperparathyroidism (GCM2), renal hypophosphatemia with or without rickets (SLC34A1, SLC34A3, SLC9A3R1, VDR, and CYP27B1), DiGeorge syndrome (TBX1 and NEBL), and hypophosphatasia (ALPL)." (PMID 38586466, 2024).
Arrhythmia (2 papers, 2021 to 2022). Any cardiac rhythm other than the normal sinus rhythm. "A GWAS analysis has revealed that NEBL p.A219D (rs2296610) is significantly correlated with AF, suggesting that the NEBL mutation may probably associate with an increased risk of arrhythmia." (PMID 36303204, 2022).
breast carcinoma (2 papers, 2014 to 2020). "Our data showed that decreased expression of NEBL is associated with 36% of 15-year survival rate for breast cancer, suggesting a protective role of this protein when overexpressed." (PMID 25057922, 2014). "Second, compared to conventional breast cancer, somatic mutations in MUC17, FLG and NEBL were of much higher prevalence among EOBC patients." (PMID 32731431, 2020). "Taken together, these findings suggest that the three hubs, NEBL, HBEGF, and PAPD7, in the differential networks play important roles in growth and development of breast cancer cells, and may thus become potential novel therapeutic targets." (PMID 25057922, 2014).
colon cancer (2 papers, 2023 to 2025). "Among the 14 model genes, the expression levels of FZD3, CDC25C, CDCA2, NEBL, and HMMR were positively correlated with better prognosis of colon cancer." (PMID 41425852, 2025).
allergic rhinitis (1 paper, 2014). Inflammation of the nasal mucous membranes caused by an IgE-mediated response to external allergens. "Interestingly, there was also induction of ciliary genes (BBS1, NEBL, NME7) of which NEBL and NME7 in allergic rhinitis patients with or without asthma while BBS1 exclusively in patients with allergic rhinitis." (PMID 24475887, 2014).
Arthritis (1 paper, 2021). Inflammation of a joint. "The top-ranked genes associated with arthritis and skeletal disease in humans were Pitx1, coiled-coil domain containing 6 (Ccdc6), HECT and RLD domain containing E3 ubiquitin protein ligase family member 1 (Herc1), nebulette (Nebl), Sh3bp4, and Zfp341." (PMID 33473114, 2021).
Brugada syndrome (1 paper, 2022). A genetically heterogeneous condition characterized by complete or incomplete right bundle branch block accompanied by ST elevation in leads V1-V3. "Therefore, we proposed that truncated mutations of NPPA (p.R107X) and NEBL (p.R882X) may induce Brugada syndrome by aberrantly affecting the cardiac sodium channel, similar to loss-of-function of the sodium channel." (PMID 36303204, 2022). "The truncated mutations of NEBL (p.R882X) and NPPA (p.R107X) may induce Brugada syndrome by abnormally affecting cardiac sodium channel." (PMID 36303204, 2022).
deafness (1 paper, 2024). An inherited or acquired condition characterized by the complete loss of the ability to hear from one or both ears. "The NEBL gene has been found deleted in two patients with DiGeorge syndrome type 2, who showed cardiac defects, but not in two patients with the more distal deletion, which is associated with hypoparathyroism, deafness, and renal dysplasia." (PMID 38586466, 2024).
depression disorder (1 paper, 2012). "In previous SNP level analyses, ERG, NEBL, CADPS2, GABBR2, and HDAC9 genes have been reported to be related with neuropsychiatric diseases such as BD, depression disorder, and schizophrenia." (PMID 22901090, 2012).
developmental delay (1 paper, 2025). "Deletions involving the Nebulette gene (NEBL; MIM: 605491) have been reported in patients with craniofacial dysmorphism, developmental delay, and cardiac anomalies." (PMID 41465143, 2025).
diabetes (1 paper, 2025). "A diabetes-specific targeted analysis showed negatively enriched Z-disc and contractile gene sets enriched due to the downregulation of CASQ2, peripherin (PRPH), nebulette (NEBL), titin-cap (TCAP), and LIM domain-binding proteins LDB3, PDLIM4, and PDLIM5 (Dataset EV36)." (PMID 40759793, 2025).
hypocalciuric hypercalcemia (1 paper, 2024). "Importantly, another index case with hypocalciuric hypercalcemia (CA0068) of our cohort had a nonsense variant of uncertain significance (p.Try89*) in the NEBL gene." (PMID 38586466, 2024).
leprosy (1 paper, 2017). Leprosy is a chronic infectious disease affecting primarily the skin and peripheral nervous system. "Indeed, a strong host genetic contribution to leprosy susceptibility has been well established through the identification of leprosy susceptibility genes by both positional cloning (PARK2, LTA, HLA-C, MRC1) and candidate gene approaches (e.g. TLR1, TNF, CUBN and NEBL)." (PMID 28793313, 2017).
myocardial diseases (1 paper, 2025). "We also found potentially pathologic mutations in genes ANXA6 and FEM1 A and obtained data supporting the role of NEBL in myocardial diseases." (PMID 40442228, 2025).
cancer (8 papers, 2008 to 2025). A tumor composed of atypical neoplastic, often pleomorphic cells that invade other tissues. "NEBL is also a commonly distinguishable gene that serves as a prognostic factor in various cancers, according to previous microarray results." (PMID 36241983, 2022). "Because the nebulette protein encoded by the NEBL gene mostly functions to stabilize actin filaments, the expression level of NEBL may reflect the extent of focal adhesion of anchored cancer cells." (PMID 36241983, 2022).
tumor (7 papers, 2017 to 2025). "The results showed that NEBL, PDGFRA and ZBTB4 were upregulated in OC tissues compared to in normal ovarian tissues, whereas WDR91 were downregulated in tumor tissues." (PMID 34484284, 2021). "The expression of NEBL was also lower in the tumor, but the difference was not significant (p = 0.17)." (PMID 29848370, 2018).
NEBL also shares sentences with these, for which no sentence is quoted: bladder cancer (3 papers); atrial fibrillation (2); cervical cancer (2); endocardial fibroelastosis (2); asthma (1); atherosclerosis (1); channelopathies (1); cognitive decline (1); coronary aneurysm (1); COVID-19 (1); diabetic retinopathy (1); endometrial cancer (1); glioma (1); hepatocellular carcinoma (1); Hypertension (1); hypertrophic cardiomyopathy (1); hypoparathyroidism (1); hypophosphatasia (1); liver cancer (1); lymph node metastasis (1); nasopharyngeal carcinoma (1); neuroblastoma (1); non-small cell lung carcinoma (1); pituitary adenomas (1); primary hyperparathyroidism (1); psychiatric disorder (1); renal dysplasia (1); rickets (1); schizophrenia (1); skeletal disease (1).
A further 3 diseases each share a sentence with NEBL in 1 paper.